CXCL1 (C-X-C motif chemokine ligand 1)
Diseases named in the same sentence as CXCL1 in open-access papers (continued):
Sharing a sentence is not in itself a finding about the gene and the disease.
psoriasis (90 papers, 2009 to 2026). An autoimmune condition characterized by red, well-delineated plaques with silvery scales that are usually on the extensor surfaces and scalp. "Further examination of gene signature in KCs indicated decreased expression of various psoriasis hallmark genes, such as S100a8, S100a9 and Cxcl1 in K14Cre/+Lztr1fl/fl KCs compared to Lztr1fl/fl KCs." (PMID 41162356, 2025). "They introduced Card14ΔE138K/A mutations in mice with psoriasis and found an up-regulation of pro-inflammatory cytokines, IL-23, IL-19, IL-22 and IL-17; chemokines Cxcl1, Ccl20, and Cxcl2; and antimicrobial peptides, Lcn2 and Defb4." (PMID 36012602, 2022). "They observed that the N4BP1-deficient mice developed exacerbated psoriasis with more epidermal hyperplasia, inflammatory cell infiltration, and serum CXCL1 level compared to WT mice." (PMID 33990547, 2021). "Taken together, loss of N4BP1 results in not only abnormal keratinocyte proliferation but also abnormal neutrophil maturation and infiltration by directly controlling JunB, FosB, and CXCL1, respectively, leading to susceptibility to psoriasis." (PMID 33990547, 2021). "We found that, upon IL-36 stimulation, IκBζ was actively recruited to the promoter regions of its target genes, including genes encoding for the chemokines Csf3, Cxcl1, and Cxcl2 and the psoriasis-associated antimicrobial proteins Defb4 and S100a9." (PMID 31622280, 2019). "Moderate to severe psoriasis (PASI ≥ 12) was associated with higher S100A9 and CXCL1 expression levels in seemingly healthy skin than in patients with mild psoriasis (PASI < 12)." (PMID 28790368, 2017). "WY14643 treatment significantly downregulated psoriasis‐associated inflammatory cytokines and chemokines (Il17a, Il1b, Cxcl1, Cxcl2, Cxcl3, Cxcl15, and Csf3) as well as the antimicrobial peptides S100a8 and S100a9 in IMQ‐induced skin lesions at the transcriptional level." (PMID 40878384, 2025). "Molecular analysis of the skin of IgG- and anti-IL36R-treated K14-IL17Aind mice revealed effective suppression of psoriasis-associated cytokines (Il36a, Il36g, Il36b, Il23a, and Tnf), chemokines (Cxcl1, Cxcl5, and Ccl2) and antimicrobial-peptides (such as Defb4) on mRNA level." (PMID 38162658, 2023). "In addition, mice deficient in MKP1 overproduce pro-inflammatory cytokines, and MKP1 knockout mice are highly susceptible to imiquimod-induced psoriasis, in which enhancement of p38 phosphorylation and increased Cxcl1 and Cxcl2 expression are also observed." (PMID 36825199, 2023). "Among others, important psoriasis-associated target genes of IκBζ include certain chemo- and cytokines (e.g., Cxcl1, Cxcl2, Cxcl5, Ccl3, and Il17c) as well as antimicrobial proteins, such as S100 calcium-binding proteins (e.g., S100a9), β-defensin-2 (Defb4), and lipocalin-2 (Lcn2)." (PMID 31622280, 2019). "Additionally, HDBECs cultured with IL-17, TNFα, and IFNγ, three cytokines heavily implicated in psoriasis pathogenesis, resulted in upregulation of IL-8, CXCL1, CXCL10, and CCL5." (PMID 25369198, 2014). "Moreover, mice with keratinocyte‐specific Fads2 knockdown exhibited increased mRNA levels of psoriasis‐associated inflammatory mediators, including Il17a, Il1b, and Cxcl1, in both the dorsal and ear skin, and greater neutrophil infiltration was confirmed by flow cytometry." (PMID 40878384, 2025). "They further demonstrated that psoriasis-specific COL6A5+ fibroblasts differentiate into CXCL1+ fibroblasts, subsequently promoting neutrophil chemotaxis and tissue infiltration." (PMID 40486514, 2025). "To confirm the results obtained by RNA‐seq, we performed qPCR to detect and quantify CXCL1, CXCL2, CXCL8, CSFR3, OSM and TREM1, in addition to the psoriasis‐associated genes IL‐17A and IL‐23." (PMID 40181552, 2025). "Chemokines encoded by CCR7, CCL2, CCL19, CXCL8, CXCL1, and CXCL2 genes have been identified as potential biomarkers of psoriasis." (PMID 40906403, 2025).
psoriasis (continued). "TNF‐α, IL‐1β, IL‐23, IL‐17, IL‐22, Cox2, and iNOS are all inflammatory cytokines involved in the pathogenesis of psoriasis, and CXCL1, CXCL8, and CCL20 are antimicrobial peptides and chemokines produced by keratinocytes." (PMID 38967379, 2024). "For example, increased K17 expression upregulates the expression of multiple proinflammatory cytokines and chemokines, including IFN-γ, IL-22, and CXCL1, and plays an important role in the development of psoriasis." (PMID 38730319, 2024). "Our results also show that IL-17A (a critical proinflammatory cytokine in the pathogenesis of psoriasis) induced increased glycolysis, lactate production, and psoriasis-related factors, including the expression of CXCL1/2 and IL-1α/β, in mouse primary KCs." (PMID 37303600, 2023). "Next, to examine the influence of skin inflammation levels, we measured the expression of inflammatory cytokines related to psoriasis and confirmed that Il17a, Tnf-α, and Cxcl1 mRNA expression in IMQ-induced lesions decreased after treatment with BZLF." (PMID 36950008, 2023). "Apart from macrophage mannose receptor involved in the regulation of psoriasis, mannan was shown to promote keratinocytes to secrete CXCL1 and enhance the infiltration of neutrophils during the disease." (PMID 36645209, 2023). "In support of the Role of IL-17A in the Psoriasis Pathway, CXCL1, CXCL3, CXCL6, S100A8, S100A9, and CCL20 in the shared signature were all upregulated in both psoriatic skin and colon lesional tissues." (PMID 36396672, 2022). "CXCL1 is one of the factors involved in the inflammatory responses that are responsible for skin lesions in psoriasis; other factors include the IL-23→Th17 cells axis, TNF-α and interferon-γ (IFN-γ)." (PMID 36613652, 2022). "Increased K17 expression in psoriatic lesional skin upregulates the expression of multiple proinflammatory cytokines and chemokines, including IFN-γ, IL-22, and CXCL1, and plays an important role in the development of psoriasis." (PMID 35178048, 2022). "According to our analysis, with the treatment of immunosuppressants in psoriasis, the expression of IL-37 increased gradually, while IL-19, CXCL1, CXCL2, CXCL13 decrease gradually." (PMID 36389813, 2022). "Together with mast cells, neutrophils are the main source of IL-17 in psoriasis lesions, a cytokine that increases the expression of chemoattractants for neutrophils, including CXCL1 in keratinocytes." (PMID 36613652, 2022). "In accordance with the accumulation of neutrophils in psoriasis, the gene expression of neutrophilic cytochemokines CXCL1, CXCL2, CXCL8, and IL-36 is upregulated in the lesional skin of psoriasis." (PMID 32070069, 2020). "In accordance with a previous report, IL-36γ and CXCL1 were increased in IMQ-induced psoriasis-like lesions in Il36rn−/− mice, abundant with NETs." (PMID 33214582, 2020). "It has been proposed, that the primary cellular effect of IL-36 cytokines in psoriasis is their impact on neutrophil inflammation through activation of neutrophil chemokines CXCL1 and CXCL8." (PMID 30634937, 2019). "IL-17 also increases expression of the antimicrobial peptide LL37, a psoriasis autoantigen that promotes production of proinflammatory cytokines, and C-X-C motif chemokine ligand 1 (CXCL1)." (PMID 30109481, 2018). "Cytokine and chemokine expression levels in the mouse skins were also determined because expressions of IL-6, IL-17, IL-22, CCL20 and CXCL1 were involved in the pathogenesis of psoriasis." (PMID 29138509, 2017). "Neutrophils are predominantly found in the epidermis in psoriasis and are recruited by the chemokines CXCL1, CXCL2, IL-8 and IL-18." (PMID 26573299, 2016). "Our research revealed that elevated levels of CXCL1, CXCL2, and CXCL8 in psoriasis patients are significantly associated with the infiltration of immune cells such as T cells, neutrophils, and DCs, hence providing considerable diagnostic value with an AUC of 0.989, 0.963, and 0.982, respectively." (PMID 38829444, 2024).
psoriasis (continued). "Furthermore, it has been demonstrated that suppression of miR-31-5p in keratinocytes in psoriasis suppresses NF-κB-driven promoter-luciferase activity and IL-1β, CXCL1, and CXCL5 production." (PMID 39259390, 2024). "CXCL1 is a pro-inflammatory chemokine, which is connected to fibrosis of the heart, lung, liver, and kidney tissue, as well as skin-related diseases (e.g., psoriasis, sunburn, itchy skin)." (PMID 39199207, 2024). "IL-1α, IL-1RA, and CXCL-1/2 are cytokines directly involved in psoriasis skin inflammation." (PMID 36936209, 2023). "Results: we externally applied BZLF for skin lesions in an imiquimod-induced psoriasis mouse model and found that BZLF alleviated psoriasis-like skin lesions while inhibiting the expression of Ki67 and inflammatory factors (Il17a, Tnf-α, S100a7 and Cxcl1) in skin lesions." (PMID 36950008, 2023). "Fibroblasts produced a number of chemokines (CCL13, CCL19, CCL2, CCL8, CXCL1, CXCL12, CXCL2, CXCL3) that linked to receptors expressed by myeloid cells and T cells, suggesting an important role for fibroblasts in recruiting immune cells in psoriasis." (PMID 37308489, 2023). "CXCL1 and CXCL2 recruit neutrophils, causing a breach of epidermal hyperproliferation, intraepidermal neutrophilic microabscess, which are the typical features of psoriasis." (PMID 36389813, 2022). "Lastly, the CXCL1 gene has been identified as a hub gene for mild psoriasis." (PMID 36613652, 2022). "Serum levels of CXCL1 are elevated in patients with psoriasis." (PMID 36613652, 2022). "TSG-6 produced by MSCs-IT can reduce neutrophil infiltration in psoriasis mouse model by decreasing the expression of CXCL1, which may be related to the reduced level of STAT1 phosphorylation." (PMID 36433947, 2022). "Here, we unraveled another member that is N4BP1, plays critical role both in keratinocytes and neutrophils by directly controlling mRNA stability of several key genes including JunB, FosB, and CXCL1, and through such mechanism maintains skin hemostasis to prevent the development of psoriasis." (PMID 33990547, 2021). "In addition, IL-24 overexpression in psoriasis prompts the expression of pro-inflammatory chemokines CXCL1, CXCL8, and CCL20." (PMID 34638757, 2021). "CXCL1 participates in the IL-17 signaling pathway, which is closely related to psoriasis." (PMID 31867221, 2020). "RNA-seq data from NHK treated with TNF and rhodomyrtone confirmed the inhibitory effect of rhodomyrtone, particularly on the IL-17A/TNF induction of DEFB4, IL36G, and CXCL1, all known to be highly expressed in psoriasis lesions and investigated as potential biomarkers." (PMID 30321197, 2018). "IL-6, IL-8, and CXCL-1 play active roles in the development of psoriasis." (PMID 28217129, 2017). "Several of the chemokines that were determined to be upregulated by psoriasis-associated CARD14 mutations in ECs, have been found by previous gene array studies that LS skin contains significantly higher expression of IL-8, CXCL1, and CXCL10 than does NL skin." (PMID 25369198, 2014). "Indeed, LS skin contained significantly more CCL2, CCL5, and CXCL1 compared to NL skin, in both classical psoriasis and the GEN001 patient." (PMID 25369198, 2014). "Normal human keratinocytes were found to constitutively bear the IL-17 receptor (IL-17R) and they are able to produce several IL-17-induced inflammatory and immune-related mediators implicated in psoriasis pathogenesis (e.g. IL-8, CCL20, S100A12, CXCL1, and CXCL2)." (PMID 24587313, 2014). "Furthermore, inflammatory cytokines relevant to psoriasis pathogenesis, including Il17a, Tnfa, and Il1b, as well as neutrophil‐attracting chemokines, such as Cxcl1 and Csf3, were significantly upregulated at the mRNA level in Fads2‐silenced skin lesions compared to controls." (PMID 40878384, 2025).
psoriasis (continued). "The study assessed the skin surface protein levels of psoriasis patients undergoing whole-body treatment with narrow-band UVB to evaluate whether the levels of the skin surface proteins IL-1α, IL-1RA CXCL-1/2, and hBD-1 were associated with the disease activity and severity measurements." (PMID 36936209, 2023). "In addition, pretreatment of HaCaT cells with polar microalgae extracts significantly decreased expression of IL1B, IL23, CXCL1, and IL17A mRNA, which are mediators implicated in the pathogenesis of psoriasis, compared to HaCaT cells treated with only M5 cytokines." (PMID 37438821, 2023). "Moreover,skin-specific NLRP3 suppression can inhibit the proliferation and chemotaxis ofkeratinocytes through the downregulation of IL-1β, IL-23, IL-17A, C-X-Cmotif chemokine ligand 1 (CXCL1), as well as the improvement of Treg/Th17 ratio,thus ameliorating the skin lesions induced by psoriasis." (PMID 39076663, 2022). "Consequently, we showed that the skin of IMQ-induced mice mimics the psoriatic characteristics with increased infiltration of inflammatory cells and increased levels of psoriasis-related cytokines and chemokines such as CXCL1, IL-25, IL-17A, IL-6, IL-1β, IL-36, CD4, and IFN-γ." (PMID 34641629, 2021). "Furthermore, whereas psoriasis-related genes, such as Cxcl2, Cxcl1, and Il1f6, were significantly induced in the skin of K14-IL17Aind Ctrl mice, the same genes were expressed neither in skin samples nor in keratinocytes isolated from mice harboring an additional deletion of IκBζ in keratinocytes." (PMID 31622280, 2019). "Finally, the circulating immune cells infiltrate the skin and other organs, which might be further supported by IκBζ-dependent chemokines (e.g., Cxcl1, Cxcl2), and result in the establishment of full-blown psoriasis and systemic inflammation." (PMID 31622280, 2019). "IL36G was also highly expressed in psoriasis, and correlation analysis indicated that IL36G was closely related to IL36A, IL19, CXCL1, and CXCL8, all of which participate in the pathogenesis of psoriasis." (PMID 40159643, 2025). "We identified five cytokines and receptors that intersected between urticaria, atopic dermatitis, and psoriasis: IL36G, IL20, IL1B, CXCR1, and CXCL1." (PMID 40159643, 2025). "In a murine psoriasis model, TLR2 signaling contributed significantly to the itching by mediating the expression of CXCL1/2, IL-31, IL-33, ST2, IL-6, and TNF-α." (PMID 40995100, 2025). "Proteins related to the central disease‐driving pathways of psoriasis, namely the TH1 (CCL3, CCL4, CXCL9, CXCL10, CXCL11, TNFα) and TH17 pathway (CXCL1, CCL20, IL‐17A, IL‐12B) were found elevated in lesional skin across both studies." (PMID 40970551, 2025). "The differential expression analysis identified several upregulated differentially expressed genes, including OSM, CXCL8, TREM1, CXCL1, CSF3R, BCL2A1 and CXCL2, in relapsed psoriasis skin compared with baseline lesional skin." (PMID 40181552, 2025). "Our study highlighted CCR7, CCL2, CCL19, CXCL8, CXCL1, and CXCL2 as potential inflammatory biomarkers in psoriasis, illuminating their molecular mechanisms." (PMID 38829444, 2024). "In conclusion, our study highlights six chemokine genes (CCR7, CCL2, CCL19, CXCL8, CXCL1, and CXCL2) as potential biomarkers in psoriasis, providing insights into the immune and inflammatory responses as pivotal instances in disease pathogenesis." (PMID 38829444, 2024). "The study highlights six chemokine genes (CCR7, CCL2, CCL19, CXCL8, CXCL1, and CXCL2) as potential biomarkers in psoriasis, which are significantly involved in immune and inflammatory responses." (PMID 38829444, 2024). "Our findings confirm that the skin surface hBD-2, IL-1α, CXCL-1/2, and CXCL-8 are markers for the psoriasis severity." (PMID 38003437, 2023). "IL-17 activates epidermal keratinocytes through IL-17R, producing pro-inflammatory cytokines and chemokines, such as IL-1, IL-6, CXCL1, and CCL20, which are known to induce and propagate psoriasis inflammation." (PMID 38203230, 2023).
psoriasis (continued). "IL-17, alone or synergistically with TNF-α acting on keratinocytes, results in the transcription of many psoriasis-related genes, including CCL20, CXCL1, -2, -3, and -8 chemokines." (PMID 35216231, 2022). "It is well known that keratinocytes attract neutrophils by releasing CXCL-1 and CXCL-8 expression in the context of psoriasis." (PMID 35401573, 2022). "SerpinB7 knockdown in HaCaT cells drastically increased the expression of psoriasis-related chemokines (CCL20, CCL27, CXCL1, CXCL2) and antimicrobial peptides LL37 and S100A8 in the M5-stimulated in vitro psoriatic model." (PMID 35864103, 2022). "In psoriasis, MMP9 also significantly upregulates the mRNA levels of ICAM-1, IL1β and CXCL1 in vascular endothelial cells (VECs), which enables VECs interaction with more leukocytes." (PMID 34122426, 2021). "After injection of LCN2 into imiquimod (IMQ)-induced psoriasis-like skin, the mRNA expression levels of IL17A, CXCL1, CCL20, S100A7, and other cytokines and chemokines increased, which supports our analysis results." (PMID 33613635, 2021). "Leptin induces IL-6, CXCL-1, IL-8 and MCP-1 production, which is involved in the hyperproliferation of the epidermis in psoriasis." (PMID 32397568, 2020). "Previous studies revealed an important contribution of keratinocyte-derived CXCL1 and CXCL2 to the development of psoriasis, as these chemokines trigger the infiltration of neutrophils into the skin." (PMID 31622280, 2019). "IL-17A not only contributes to the epidermal abnormalities typical of psoriasis, but also induces the expression of chemokines in keratinocytes such as GRO-α (CXCL1) and IL-8 (CXCL8), which orchestrate the recruitment of neutrophils to psoriatic lesions." (PMID 25828362, 2015). "IL-8, CXCL1, and CXCL2 have been reported upregulated in the lesional skin of patients with AD or psoriasis." (PMID 24586752, 2014). "We therefore evaluated the expression of selected cytokines and chemokines thought to contribute to initiation or maintenance of the inflammatory cascade in human psoriasis (e.g., TNF, IL22, IL6, CXCL1)." (PMID 21483750, 2011). "Similarly, in psoriasis, TOPK regulates neutrophil chemokines such as CXCL1, CXCL2, and CXCL8 by activating STAT3 and NF-κB p65 in keratinocytes, thereby promoting neutrophil infiltration and psoriasis progression." (PMID 41362722, 2026). "RT-qPCR experiments further confirmed that CXCL16 expression was significantly elevated in MDMs from psoriasis patients compared to healthy controls, while no statistical differences were observed for CXCL1, CXCL3, and CXCL5." (PMID 40722833, 2025). "Skin surface levels of IL-1α, IL-1RA, CXCL-1/2, and hBD-1 detected on the skin of healthy volunteers appeared similar to the levels captured on the non-lesional skin of psoriasis patients." (PMID 36936209, 2023). "A recent study has shown that disruption of the epidermal barrier can exacerbate psoriasis by unregulated keratinocyte proliferation and the overexpression of S100A8, S100A9, CXCL1, and other molecules, indicating a defect in ceramide-dependent epidermal barrier signaling and function." (PMID 36837912, 2023). "Using TAP technology, it was observed that there were clear differences in levels of IL-1α, IL-1RA, CXCL-1/2, and hBD-1 between psoriasis lesional and non-lesional skin." (PMID 36936209, 2023). "Comparing the levels of skin surface IL-1α, IL-1RA, CXCL-1/2, and hBD-1 captured from psoriasis patients’ lesional and non-lesional skin revealed statistically higher levels of IL-1RA (p < 0.001), CXCL-1/2 (p < 0.01), and hBD-1 (p < 0.05) on lesional skin." (PMID 36936209, 2023). "The transcriptional expressions of Cxcl1, Cxcl2, Il-1β, Il-1α, S100A8, S100A9, Il-6, and Vegf were significantly decreased in skin lesions of K14.Bsgfl/fl mice, indicating the proinflammatory role of the epidermal expression of CD147 in psoriasis." (PMID 37303600, 2023).